TNF (tumor necrosis factor)
Diseases named in the same sentence as TNF in open-access papers (continued):
Sharing a sentence is not in itself a finding about the gene and the disease.
tumor (continued). "Skeletal muscles are subjected to damaging stimuli, primarily due to cytokines produced by tumor cells, such as IL-6, TNF-α, and IFNγ, responsible for inflammation." (PMID 33158194, 2020). "Associations among fecal occult blood test (FOBT) result, CD68, IL-6, and TNF-α expression in tumor cells." (PMID 33643891, 2020). "On this note, the tumor microenvironment secretes cytokines (e.g., SDF-1, EGF, PDGF, TNF-α and IL-8) that recruit MSCs into the tumor mass." (PMID 33143238, 2020). "Tumor necrosis factor alpha (TNF-α) plays major roles in the growth, invasion, and metastasis of neoplasm called a perigenetic pathway." (PMID 32149129, 2020). "On one hand, γδ T cells can directly kill tumor cells through their strong cytotoxic effects, which usually depends on their production of interferon γ (IFNγ) and tumor necrosis factor-α (TNF-α)." (PMID 32413966, 2020). "It has been shown in different murine tumor models that TNF-α secreted by CD4+ T cells, and partially by CD8+ T cells, induces myelopoiesis, which increases the frequency of MDSCs." (PMID 32793192, 2020). "We tested the effect of inflammatory cytokines commonly found in tumor microenvironment including IL-1β, IL-6, IL-10, TNF-α, and IFN-γ on TDO2 expression on MUM cells." (PMID 32050636, 2020). "TRAIL/Apo2L is a cytokine of the tumor necrosis factor (TNF) gene superfamily that selectively induces apoptosis in many tumor cells while leaving normal cells intact and remains an attractive candidate for antitumor therapies." (PMID 30718520, 2019). "Pretreatment with PT-cAu-TNF-α induced vascular damage and significantly reduced tumor survival to 0.005%." (PMID 31315232, 2019). "In vitro functional studies using THP-1 derived macrophages revealed CD38 expression to be associated with the M1 state, characterized by CD80 expression and secretion of TNFα and IL-6, all of which contribute to the anti-tumor immune response." (PMID 31552039, 2019). "Through activation of NF-κB, TNF can induce the expression of a variety of pro-tumor genes including MMPs, COX2, and VEGF." (PMID 31174326, 2019). "For example, astragalus saponins, astragalus and angelica polysaccharides, ferulic acid, and Z-ligustilide are known to suppress expression of some tumor-promoting cytokines, such as IL-1β, IL-6, and TNF-α." (PMID 31781219, 2019). "Tumor cells produce cancer-related inflammatory mediators, such as tumor necrosis factor-α, interleukin-3 (IL-3), and IL-6." (PMID 31286873, 2019). "M1 macrophages are largely considered to be “anti-tumor” based on their expression of the pro-inflammatory cytokines, interleukin-1 (IL-1), IL-12, TNF-α, and inducible nitric oxide synthase - all of which have been shown to oppose tumor progression." (PMID 30847405, 2019). "The tyrosine phosphorylation of STAT1 and STAT3 are catalyzed by Janus kinase (JAK) and control the STAT1 and 3 downstream transcriptome, including the TGF-B1 and TNF gene network, and promote tumor progression and chemoresistance in cancer cells." (PMID 31182137, 2019). "In our study, we found that deletion of TRIM59 further enhanced the tumor-promoting actions of M2 macrophages by inducing production and the release of TNF-α." (PMID 31600735, 2019). "CD46 activation on γδ T-cells has also been shown to directly suppress their IFNγ and TNFα production, which can further lead to a pro-tumor environment." (PMID 31164885, 2019). "To investigate the role of TNF-α, we analyzed the association of the level of NF-κB p50 transcripts with the methylation status of the NFKB1 and the RELA genes in tumor tissues depending on the expression of TNF-α." (PMID 31382678, 2019). "SM-164, GDC-0152 and LCL161 potently sensitized cells from most tumors to killing by TNFα, although we observed some inter-tumor variability in the magnitude of this effect." (PMID 31521127, 2019). "Another interesting observation reported was the ability for the Au-PEG-TNF nanoparticles to diminish a tumor mass compared to “free” TNF." (PMID 31147786, 2019).
tumor (continued). "Some of these factors elevated in obese subjects, such as tumor-promoting cytokines (e.g., TNF-α and IL-6) and monocyte chemo-attractants (e.g., MCP-1), are implicated in PDAC development and progression." (PMID 31277269, 2019). "For example, pDC recruited by ovarian tumor ascites support tumor vascularization through the secretion of angiogenic cytokines TNF-α and IL-8." (PMID 30979057, 2019). "Significantly, the GBM cohorts harboring a high-level H2AFJ transcript combined with high-level expression of TNF-α/NF-κB geneset, IL-6/STAT3 geneset or HADC3 were associated with a shorter time to tumor repopulation after initial treatment with TMZ." (PMID 31906036, 2019). "Recently, it had been demonstrated that oncolytic adenoviruses express interleukin-2 (IL-2), and the tumor necrosis factor alpha (TNF-a) can achieve an anti-tumor immunomodulatory effect similar to lymphodepletion." (PMID 31781493, 2019). "Taken together, this study has shown for the first time that astrocytes produce more TGF-β2 in response to tumor cell-derived IL-1β and TNF-α." (PMID 31602400, 2019). "Lymphocytes can secrete cytokines such as IFN-γ and TNF-α, thus controlling tumour growth and improving the prognosis of cancer patients." (PMID 30824727, 2019). "A higher neutrophil count upstreams chemokine production: interleukin-1, interleukin-6 (IL-6), and tumor necrosis factor, therefore enabling tumor progression." (PMID 30800188, 2019). "Here, we demonstrate that TNFα fused to a new tumour ECM‐recognising peptide specifically accumulates in desmoplastic tumours, increasing immune cell accumulation and ECM degradation." (PMID 31709774, 2019). "Similar to what has been shown for other ECM‐reducing strategies, TNFα‐CSG enhanced tumour perfusion and uptake of MRI contrast agents, indicating potential use for cancer imaging." (PMID 31709774, 2019). "ANF in combination with PD-L1 blockade exerted potentiated effects in induction of infiltration of CD3, CD8, CD4, and B220 positive cells into tumor tissues, and upregulation of IFNγ and TNFα expression by the lungs." (PMID 30850589, 2019). "Aside from the role of IFNγ in immunoediting, thereby preventing primary tumor formation, defects in both IFN and TNF signaling have been associated with increased cancer risk." (PMID 30833945, 2019). "A previous study reported that deletion of IL6 or TNFα in a mouse model of HCC accelerated tumor development." (PMID 31552039, 2019). "The substance also inhibited the tumor-promoter-stimulated inflammation, TNF-α production, and activation of epidermal ODC." (PMID 31394732, 2019). "Increased accumulation of IONPs in TNFα‐CSG‐treated tumours was also confirmed by immunohistochemistry." (PMID 31709774, 2019). "Tumour CD45+/CD11b− cells from mice treated with TNFα‐CSG expressed twofold to 20‐fold higher levels of mRNAs for multiple proteases than cells from the CSG‐treated tumours." (PMID 31709774, 2019). "TNFα is known to trigger apoptosis in tumor cells through blocking NF-κB signaling, and thus considered a possible mediator of the tumoricidal effect of LF-IC-primed monocytes." (PMID 31600968, 2019). "Pro-inflammatory cytokines such as tumor necrosis factor (TNF)-α, interleukin (IL)-1β, and IL-6 are reported to participate in chronic inflammation of tumor microenvironment, thereby creating a favorable environment for tumor progression and metastasis." (PMID 31252615, 2019). "As part of the systemic inflammatory response to a tumour or from the tumour itself, inflammatory mediators are released, including interleukin-1 (IL-1), IL-6, tumour necrosis factor- (TNF-) α, and acute-phase reactants." (PMID 31781312, 2019). "A recent study has shown that rosmarinic acid prevents the secretion of VEGF, IL-6, TGF-β, TNF-α, and NF-kB in H22 tumor-bearing mice, proving its potential as an antitumor agent." (PMID 30871059, 2019).
tumor (continued). "It has been observed that TANs actively communicate with tumor cells through growth factors or inflammatory cytokines such as TNFα, CCL2, IL-8, and IL-17a, which can promote tumorigenesis and progression." (PMID 30616627, 2019). "To understand if NFATc3 is a critical factor for cytokines and chemokines known to be involved in tumour growth, we evaluated the impact of nuclear NFATc3 on TNF-α, CXCR-3, GM-CSF, IL-2 and CCL-2 mRNA expression." (PMID 31249342, 2019). "During these courses, the TNF-α signaling pathway is involved in the fusion between cancer cells and MSCs to generate tumor initiating-like hybrids." (PMID 31380426, 2019). "Tumor necrosis factor-alpha (TNF-α) is an important inflammatory factor in the tumor microenvironment that is generated by tumor cells and stromal cells." (PMID 31500658, 2019). "In a similar study, TDEs containing FasL and tumor necrosis factor α were found to induce T-cell apoptosis, thereby establishing an immunosuppressive tumor microenvironment to support tumor progression." (PMID 31620359, 2019). "These inflammatory mediators including interleukin-6 (IL-6), the chemokine IL-8, and tumor necrosis factor (TNF-α) promote the recruitment of immune cell populations to the tumor site." (PMID 31531020, 2019). "TNF-α is a type of cytokine produced by macrophages that is directly toxic to tumor cells, leading to hemorrhagic tumor necrosis." (PMID 31467867, 2019). "Tumor expression of IL1β and TNFα augmented within 24 h and IL6 within 12 h after the LPS treatment." (PMID 31712726, 2019). "TNF-α+ production by T cells in draining lymph nodes were comparable between WT and Stat4−/− tumor bearing mice, while splenic T cell TNF-α production was slightly attenuated in Stat4−/−tumor bearing mice." (PMID 32010142, 2019). "Especially in the aspects of anti-inflammatory and anti-tumor, it has been found that gamoic acid can inhibit many cell signaling pathways, such as nuclear factor-kappa B (nf-κb), tumor necrosis factor-α (TNF-α), and iNOS." (PMID 31572177, 2019). "For instance, IL-37 reduces the secretion by both immune cells and tumor cells of IL-6, IL-1β and tumor necrosis factor alpha, cytokines known to play a role in tumor progression." (PMID 31231372, 2019). "The tumor microenvironment such as tumor necrosis factor alpha (TNF-α) secretion and stimuli by macrophages, can also increase the expression of MMPs6." (PMID 30787353, 2019). "But tumors also precondition target organs creating a hospitable niche by the mobilization of bone marrow-derived myeloid cells, tumor secreted factors such as VEGF, TGF, TNF, and tumor released-exosomes which also modulate the tumor microenvironment." (PMID 31001273, 2019). "Purified PDATME DC produced markedly elevated TNFα, IL-6, and IL-10 in culture compared with splenic DC from tumor-bearing hosts." (PMID 30926808, 2019). "Our previous experiments determined an enhanced capacity of Ptpn22–/– CD8+ T cells to produce IFN-γ and TNF in response to low-affinity peptide antigens and mediate tumor rejection upon ACT." (PMID 31335326, 2019). "These factors secreted by tumor cells include interleukins, tumor necrosis factor-α (TNF-α), stromal cell-derived factor 1 (SDF-1), and other identified and unidentified inflammatory transmitters." (PMID 31358061, 2019). "M1 macrophages produce inflammatory cytokines, such as IL1ß and TNF, play a role in Th1 responses and in the killing of pathogens and tumor cells." (PMID 31191690, 2019). "In direct contact co-culture system, IL-35 stimulation notably reduced the secretions of IFN-γ, IL-12p70, IL-6, IL-8, and TNF-α in CD8+ T cells purified from non-tumor and tumor site." (PMID 31134088, 2019). "Some examples of cytokines that are involved in inflammation and the tumor microenvironment include tumor-necrosis factor-α (TNF-α), interleukin-6 (IL-6), transforming growth factor ß (TGF-β), and interleukin-10 (IL-10)." (PMID 30838040, 2019).
tumor (continued). "Synbiotics-treatment suppressed DSS-induced expression of IL-6, STAT-3, COX-2, and TNF-α gene transcripts in normal colonic epithelium, indicating the possibility of suppressing tumor development." (PMID 31242213, 2019). "Meanwhile, in B16F10 melanoma, T241 fibrosarcoma, LLC, and MMTV-PyMT-derived lung adenocarcinoma, tumor-induced TNF-α stimulates the NF-kB signaling pathway to express proto-oncogene MET in neutrophils." (PMID 31474975, 2019). "TNF-α is an inflammatory cytokine produced mainly by macrophages/monocytes as well as tumour cells during acute inflammation and responsible for a diverse range of signalling events within cells." (PMID 30923340, 2019). "Adenosine inhibits NK cell anti-tumor activities by blocking granzyme exocytosis, impairing perforin and Fas ligand-mediated cytotoxic activity and limiting IFNγ/TNFα release." (PMID 31057536, 2019). "Various tumor-induced factors have been shown to stimulate osteoclastogenesis, including inflammatory cytokines, such as TNF-α." (PMID 31835378, 2019). "Tumor cells with high expression of TNFRSF1B resist TNF-induced cell death by ligand binding to TNFRSF1B." (PMID 32039005, 2019). "Inflammatory mediators can stimulate cell proliferation and motility, thus driving tumor aggressiveness; but factors such as TNF-α also convey powerful growth-restraining and pro-apoptotic signals." (PMID 30538286, 2019). "TNFα plays a pivotal role during steady state or pathologic conditions, for example, infections, injury, inflammation and tumour development." (PMID 30995806, 2019). "TNF-α is a pro-inflammatory cytokine made by activated immune cells leading to suppression of tumor proliferation." (PMID 30509964, 2019). "TNF-α-activated MAPKs, Akt, and IκB-α signaling pathways have been involved in tumor progression via AP-1 or NF-κB transcriptional activities." (PMID 31540489, 2019). "Tumor necrosis factor alpha (TNF-α) is a strong proinflammatory cytokine with anti-tumor activity both in vitro and in vivo." (PMID 31179236, 2019). "Malignant epithelial cells secrete cytokines, such as TNFα, IL-6, and IL-11, which inhibit the differentiation of the fibroblasts that surround tumor cells into adipocytes and increase their aromatase activity and expression." (PMID 31412584, 2019). "MEK-I modulates in–vitro the immune micro-environment through a transcriptionally decrease of PD-L1 expression, enhance of MHC-I expression on tumor cells, increase of the production of several cytokines, like IFNγ, IL-6, IL-1β and TNFα." (PMID 31196138, 2019). "The presence of the HPV was associated with increased inflammatory cytokines (IL-1, IL-6, IL-17, TGF-β, TNF-α, and NF-kB) and tumor progression." (PMID 30642295, 2019). "It has been reported that as a result of treatment such as hypoxia or radiation, levels of TNF-α, TGF-β, PDGF, CXCL12, MMP, and HIF are elevated within the tumor associated EVs." (PMID 31146452, 2019). "This study also reported that endotrophin facilitate tumor cell proliferation and metastasis through TGF-β activation as well as promote inflammation in the tumor microenvironment by upregulating inflammatory markers such as interleukin-6 and TNF-a." (PMID 30841909, 2019). "Neutrophils can be recruited by the tumor through the production of cancer-related chemokines and cytokines (e.g., IL-6 and TNF)." (PMID 31817109, 2019). "The cytokine tumor necrosis factor alpha (TNF-α) works immunosuppressive by increasing the expansion of immunosuppressive myeloid cells and regulatory T cells at the tumor site 202,203." (PMID 31695800, 2019). "TAMs are typically polarized in the pro-tumor ‘M2′ subtype which secrete high levels of IL-10 and TNFα, and decreased IL-12 to promote the immunosuppressive environment and increase invasiveness in cancer cells." (PMID 31443240, 2019).
tumor (continued). "Tumor-bearing rats receiving Oro Inca oil displayed an improvement of body weight, diminished IL-6, and TNF circulating levels, as well as decreased triacylglyceride (TAG) levels, demonstrating that ALA-rich oil also has anti-cachectic effects." (PMID 31035457, 2019). "To summarize, TNF implication in cancer development is rather complex with a balance between high, and low levels of TNF having opposing effects on tumor growth." (PMID 31417576, 2019). "It was demonstrated that despite its potential anti-tumor cytotoxic activities, chronic presence of TNFα in tumors has led to tumor progression." (PMID 31031757, 2019). "TNF-α exerts multiple, context-dependent actions, and has been deemed a tumor-promoting factor for its ability to promote tumor survival by indirect mechanisms (e.g. immunosuppression) or direct effects on cancer cells (e.g. induction of EMT)." (PMID 31600735, 2019). "Profiling of cytokines in ascitic fluids isolated from patients uncovered the presence of pro- inflammatory molecules, among which IL-6 and TNFα were suggested as critical mediators of tumor cell survival." (PMID 31817625, 2019). "Specifically in CC-group, a positive correlation was found between ANGPTL-4 levels and those of IL-1β, TNF-α, and NFκB in tumor, along with an association between ANGPTL-4 levels with IL-1β and MCP-1 levels in tumor; and ANGPTL-4 and IL-1β levels in MES." (PMID 31741709, 2019). "TNF, a peptide produced by macrophages and lymphocytes, has cytostatic and cytolytic effects on tumor cells in vitro as well as stimulates necrosis and tumor regression in vivo." (PMID 31847387, 2019). "M1-like macrophages existed in the CC tumor stroma with a declined expression of M1-like markers such as IL-6, TNF-α and iNOS and tendedto transfer to M2-like phenotype under the influence of tumor cells." (PMID 31284453, 2019). "Mechanistically, TNF blockade prevented anti-PD-1-induced AICD of tumor-infiltrating lymphocytes (TILs) and decreased their PD-L1 and TIM-3 expression." (PMID 31727152, 2019). "Mast cells exert immunosuppression, releasing tumor necrosis factor alpha (TNF-α) and IL-10, which are essential in promoting the immune tolerance mediated by regulatory T (Treg) cells, and stimulate immune tolerance and tumor promotion." (PMID 30678047, 2019). "TNF-α markedly promotes tumor lymphangiogenesis and lymphatic metastasis through TNF-α-TNFR1 signaling pathway, activating inflammatory macrophages and tumor-associated macrophages (TAMs) to produce high levels of VEGF-C." (PMID 30847024, 2019). "A variety of cell culture studies have shown that ZnO NP can induce cytokines such as IFN-γ, TNF-α, IL-2, and IL-12 which are known to regulate the tumor microenvironment." (PMID 31771091, 2019). "In conclusion, pro-inflammatory molecules such as IL-6, IL-8, and TNF-α can lead to Notch signaling activation, enhancing tumor-promoting effects on epithelial cells." (PMID 30917608, 2019). "When the expression levels of cytokines were examined in mice treated with AOM/DSS, we found increased mRNA expression levels of IL-6, IL-11, and TNFα in tumor tissues from Tg-tRXRα mice." (PMID 30931933, 2019). "Tumor necrosis factor-alpha (TNF-α) plays a key role in promoting tumor progression, such as stimulation of cell proliferation and metastasis via activation of NF-κB and AP-1." (PMID 31540489, 2019). "TNFα and IFNγ, for example, were shown to have both promoting and inhibitory effects on tumor growth." (PMID 30833945, 2019). "ILC1s in response to IL-12, a potent antitumor cytokine, produce the effector cytokines, IFNγ and TNFα, to limit tumor growth in a melanoma mouse model." (PMID 32117199, 2019).